ATP1A1 (ATPase Na+/K+ transporting subunit alpha 1)
Diseases named in the same sentence as ATP1A1 in open-access papers (continued):
Sharing a sentence is not in itself a finding about the gene and the disease.
glioma (10 papers, 2018 to 2025). A benign or malignant brain and spinal cord tumor that arises from glial cells (astrocytes, oligodendrocytes, ependymal cells). "Previous studies have found that overexpression of ATP1A1 is associated with the occurrence and development of several cancers such as breast cancer, non-small cell lung cancer, renal clear–cell carcinoma, and glioma." (PMID 32684846, 2020). "We found that the ATP1A1 expression level was associated with the grade of glioma." (PMID 31114755, 2019). "Expression of ATP1A2 (alpha subunit of Na/K-ATPase specific for glial cells) was higher in both glial tumors versus neuronal-specific ATP1A1 in patients on anti-seizure medications." (PMID 40867621, 2025). "Our previous study has already established a connection between ATP1A1 levels and sensitivity to bufalin, and similar findings have been observed in glioma." (PMID 38178183, 2024). "The subunit of Na+/K+-ATPase a1 (ATP1A1), which is overexpressed in GSCs, is considered as a new therapeutic target for gliomas." (PMID 36231068, 2022). "Recently, the Na+/K+-ATPase a1 (ATP1A1) subunit was described as a novel therapeutic target for gliomas." (PMID 31114755, 2019). "In our study, ATP1A1 was generally overexpressed in GSCs, and the expression level of ATP1A1 positively correlated with the pathological grade of human glioma, while the higher grade glioma is closely related to the worse prognosis of patients." (PMID 31114755, 2019). "To screen for specific molecules expressed in GSCs, we previously performed a proteomics assay comparing GSCs and differentiated glioma cells, and we found that ATP1A1 is overexpressed in GSCs." (PMID 31114755, 2019). "Both western blotting and immunohistochemical data suggested that ATP1A1 was significantly upregulated in high-grade gliomas (WHO grade III astrocytomas and GBMs) when compared with low-grade gliomas (grade I and, II astrocytomas) and normal human brain." (PMID 31114755, 2019). "ATP1A1 expression in normal brain and glioma tissues of different grades." (PMID 31114755, 2019). "We tested RNA and protein expression of ATP1A1 in glioma tissues and GSCs." (PMID 31114755, 2019). "ATP1A1 knockdown markedly changed the IC50 values of MBG for glioma cells." (PMID 29582577, 2018). "In addition, transfection experiment of ATP1A1‐siRNA was further carried out to confirm the role of sodium pump α1 subunit in the anticancer effect of MBG in human glioma." (PMID 29582577, 2018). "Taken together, these results indicate that MBG could inhibit glioma growth via binding to ATP1A1." (PMID 29582577, 2018). "For example, NKA α1 subunit (ATP1A1) is upregulated in non-small cell lung cancer (NSCLC), esophageal squamous cell carcinoma (ESCC), renal cell carcinoma, glioma, but downregulated in prostate cancer." (PMID 33868261, 2021).
renal cell carcinoma (7 papers, 2017 to 2025). "The combination of PGRMC1 and ATP1A1 protein levels can serve as a promising indicator of the prognosis of renal cell carcinoma." (PMID 38566133, 2024). "ATP1A1 may induce renal cell carcinoma cell apoptosis by mediating the Raf/MEK/ERK signaling pathway." (PMID 35928827, 2022). "However, ATP1A1 were significantly down-regulated in prostate cancer, colorectal cancer and renal cell carcinoma." (PMID 34350460, 2021). "ATP1A1 is significantly reduced in patients with renal cell carcinoma (RCC), and patients with RCC with positive ATP1A1 expression have a better prognosis." (PMID 38358909, 2024).
breast carcinoma (6 papers, 2017 to 2025). "Some studies suggest that ATP1A1 may be used as a diagnostic marker for renal cancer and breast cancer, which is related to the prognosis of tumor." (PMID 40831924, 2025). "Collectively, these findings suggest that ATP1A1 plays a more oncogenic role in TNBC than in other breast cancer subtypes." (PMID 38730618, 2024). "In addition to showing that ATP1A1 was overexpressed in breast cancer, particularly in TNBC, we found that the inhibition of ATP1A1 expression markedly reduced the proliferation and self-renewal activity of human TNBC cells in vitro." (PMID 38730618, 2024). "Kaplan–Meier survival analysis in patients classified as high risk according to their methylation beta values and gene expression indicated that OS in patients with basal-like breast cancer was significantly poorer when ATP1A1 was both hypomethylated and upregulated (p = 0.00159)." (PMID 38730618, 2024). "Similarly, the ATP1A1 lever was elevated and affected breast cancer patients’ survival, whereas ATP2A2 seemed to be neutral in respect to survival." (PMID 34684111, 2021). "ATP1A1 has been previously reported to be over-expressed in breast cancer." (PMID 31874600, 2019). "We found abnormalities inATP1A1 (coding α1-subunit) andATP1A2 (coding α2-subunit) expression in breast cancer samples relative to their expression in normal breast tissue.ATP1A1 was overexpressed approximately 1.5 times in all groups of breast cancer samples (p<0.05)." (PMID 28529692, 2017). "Finally, immunohistochemical analysis of ATP1A1 protein expression in a breast tissue microarray (TMA) that included 120 specimens of different breast cancer subtypes showed that ATP1A1 was more highly overexpressed in TNBC than in other breast cancer subtypes (Luminal A, B, and HER2+)." (PMID 38730618, 2024). "The TNBC-specific methylation and mRNA expression patterns of the ATP1A1, ADH1C, and CFH genes were also significantly altered in the TCGA cohort, depending on the breast cancer subtype." (PMID 38730618, 2024). "ATP1A1 has been reported to be overexpressed in breast cancers, but the methylation status and biological function of ATP1A1 in TNBC have not yet been elucidated." (PMID 38730618, 2024).
Hypomagnesemia (6 papers, 2019 to 2023). An abnormally decreased magnesium concentration in the blood. "Variants in ATP1A1 cause hypomagnesemia, seizures, and mental retardation 2, an autosomal dominant disease characterized by generalized seizures in infancy and significant intellectual disability." (PMID 36030824, 2022). "Previously, de novo ATP1A1 variants were reported in hypomagnesemia, spastic paraplegia, sleep disorder, intellectual disability and epileptic encephalopathy and, complex neurodevelopmental syndrome, whereas, inherited ATP1A1 variants were associated with axonal or intermediate CMT." (PMID 36738336, 2023). "Hypomagnesemia was also previously observed in children with ATP1A1 variants and epilepsy." (PMID 34717959, 2021). "Hypomagnesemia in the patients with ATP1A1 mutations may indicate more severe Na+/K+-ATPase dysfunction, because the epileptic phenotype occurs more often in individuals with hypomagnesemia." (PMID 33968856, 2021). "Therefore, ATP1A1 variants may lead to Na+ and K+ transport dysfunction and interfere with the active reabsorption of magnesium ions, resulting in hypomagnesemia." (PMID 33968856, 2021).
Intellectual disability (6 papers, 2021 to 2025). "Previous studies have reported a range of diseases related to ATP1A1 mutations, including renal hypomagnesemia, refractory epilepsy, intellectual disability, Charcot-Marie-Tooth disease (CMT), HSP, and aldosterone adenoma." (PMID 33968856, 2021). "Subsequently, heterozygous de novo mutations in ATP1A1 were reported in individuals with renal hypomagnesemia, refractory seizures, and intellectual disability, and in a child with spastic paraplegia and intellectual disability with normal nerve conduction." (PMID 34323022, 2021). "It is unclear whether ATP1A1 variants that cause other disease phenotypes, such as hypomagnesemia with seizures and intellectual disability or complex neurodevelopmental delay, may also present with peripheral neuropathies." (PMID 41048924, 2025). "Both ATP1A1 and ATP2B2 have been previously linked to neurodevelopmental disorders, including phenotypes such as intellectual disability, epilepsy, and ASD." (PMID 40836247, 2025). "Our patient with the new AD variant in the ATP1A1 gene (p.Gly549Arg) had no pyramidal signs or intellectual disability at examination, and his CMT could be classified as intermediate, in accordance with previous observations from two Chinese families." (PMID 34323022, 2021).
non-small cell lung carcinoma (6 papers, 2019 to 2026). A group of at least three distinct histological types of lung cancer, including non-small cell squamous cell carcinoma, adenocarcinoma, and large cell carcinoma. "It is reported that ATP1A1 is overexpressed in clinical specimens and cell lines of non-small cell lung cancer." (PMID 32684846, 2020).
colorectal cancer (5 papers, 2017 to 2025). A primary or metastatic malignant neoplasm that affects the colon or rectum. "Although ATP1A1 exerts oncogenic functions via the ERK5 pathway in colorectal cancer, it prolongs survival in renal carcinoma by suppressing Raf/MEK/ERK signaling, consistent with our in vitro findings, where ATP1A1 knockdown enhanced proliferation, migration, and invasion in renal cancer cells." (PMID 40821775, 2025). "Similarly, ATP1A1 level is also decreased in colorectal cancer." (PMID 28484360, 2017).
lung carcinoma (5 papers, 2016 to 2025). "Here, we report that targeting the Na+/K+-ATPase (ATP1A1) is synthetic lethal with STK11 mutations in lung cancer." (PMID 27431571, 2016). "Many lung cancers show increased expression of ATP1A1, and targeting ATP1A1 with siRNA or drugs (cardenolides) has an anti-tumor effect." (PMID 36996232, 2023). "Inhibition of ATPase Na+/K+ Transporting Subunit Alpha 1 (ATP1A1) was recently investigated by treating STK11 mutant lung cancer cells with CGs." (PMID 29117117, 2017). "Inhibition of ATP1A1 using CGs warrants exploration as a targeted therapy for STK11 mutant lung cancer." (PMID 27431571, 2016). "Some CGs, such as digoxin, digitoxin and ouabain, directly inhibited ATP1A1 and exhibited selective antitumor effects in STK11 mutant lung cancer cells." (PMID 29117117, 2017). "The cardiac glycosides (CGs) digoxin, digitoxin and ouabain, which directly inhibit ATP1A1 function, exhibited selective anticancer effects on STK11 mutant lung cancer cell lines." (PMID 27431571, 2016). "Moreover, some ubiquitination sites on the ATP1A1 and SLC3A2 transporters were upregulated, suggesting that, in ALK-driven lung cancer cells, stabilization of these transporters may not play a significant role in the metabolic changes induced by TKI treatment." (PMID 36996232, 2023).
viral infection (5 papers, 2014 to 2026). "In addition, ATP1A1 has been associated with various viral infections, for instance, SARS-CoV-2 virus RNA has interacted with host protein ATP1A1 during infection." (PMID 36835408, 2023). "ATP1A1 has not only played an important role in cancer cells, but also participated in different stages of viral infection, including viral attachment and replication." (PMID 36835408, 2023). "Moreover, the Ebola VP24 protein has interacted with ATP1A1 and treatment with ATP1A1 inhibitor Ouabain reduced viral infection." (PMID 36835408, 2023). "Collectively, these results detailed the mechanism that ATP1A1 affects PEDV replication, which may act during the attachment phase of viral infection to host cells, providing a basis of the development of novel antiviral drugs." (PMID 36835408, 2023). "Human milk blocks some enveloped, but not non-enveloped, virus infections in a primary human fetal intestinal model and the transcriptomic data points towards inhibition of entry mediated by ATP1A1." (PMID 35926873, 2022). "Knockdown of ATP1A1 significantly suppressed PRRSV-2 infection by reducing viral attachment, and the specific chemical ligands, ouabain and PST2238, effectively reduced viral internalization without affecting viral attachment, leading to decreased viral infection." (PMID 41773865, 2026).
Charcot-Marie-Tooth disease (4 papers, 2021 to 2025). An inherited degenerative disorder involving the peripheral nerves. "Charcot-Marie-Tooth (CMT) disease comprises a group of inherited peripheral neuropathies caused by pathogenic variants in various genes, including ATP1A1." (PMID 41048924, 2025). "A likely pathogenic ATP1A1 p.Ile592Thr variant was detected in an African-ancestry proband with an axonal length-dependent severe sensorimotor neuropathy with prominent peroneal muscular atrophy (foot drop) manifesting in adolescence with clumsy gait." (PMID 37712079, 2023).
colon cancer (4 papers, 2017 to 2024). "Regarding colon cancer network, genes including NME2, ATP1A1, CD24 and IFI6 showed the most connectivity." (PMID 29118934, 2017). "ATP1A1 produced 2 additional isoforms (NM_000701.7 and NM_001160233.1) in the primary colon cancer samples and their corresponding metastasis, but not in the benign colon tissues." (PMID 33907296, 2021).
epilepsy (4 papers, 2021 to 2025). A brain disorder characterized by episodes of abnormally increased neuronal discharge resulting in transient episodes of sensory or motor neurological dysfunction, or psychic dysfunction. "Functional characterization of the mutation revealed an abnormal inward current, similar to that observed in the two previously reported cases of ATP1A1 mutations associated with epilepsy." (PMID 34717959, 2021). "But the pathogenic mutations of ATP1A1 found in patients with epilepsy were all in the transmembrane regions which significantly reduced the K+ affinity and even cooperativity of K+ binding." (PMID 33968856, 2021). "To date, the phenotype spectrum of de novo ATP1A1 pathogenic variants has included neurodevelopmental disorders (including developmental delay, autism spectrum disorders, and epilepsy), emotional disorders, sleep disorders, and HSP." (PMID 33968856, 2021). "A primary disease that is relevant to ATP1A1 mutation is hypomagnesemia and epilepsy." (PMID 35751846, 2022). "EEG features of ATP1A1 mutation related epilepsy were not described in previous reports." (PMID 33968856, 2021). "ATP1A1-associated neurological diseases have been reported in 42 individuals from seven families with symptoms compatible with Charcot–Marie–Tooth syndrome and three nonrelated children with a mutation associated with epilepsy of varying severity and hypomagnesemia." (PMID 34717959, 2021).
essential hypertension (4 papers, 2013 to 2021). Hypertension that presents without an identifiable cause. "It will be important to consider these factors in testing not only the ATP1A1 12T-ins/del polymorphism but also other functional gene variants for possible association with essential hypertension in other populations." (PMID 25615575, 2015). "In summary, we have identified a 12T-insertion/deletion variant in the ATP1A1 promoter region that is associated with decreased/increased susceptibility to essential hypertension in males in a northern Sardinian population." (PMID 25615575, 2015). "Here we report experimental evidence encompassing genetic, biochemical and in vivo modeling that altogether support ATP1A1 as a hypertension susceptibility gene in males in Sardinia, Italy." (PMID 25615575, 2015). "Altogether, data support ATP1A1 as a hypertension susceptibility gene in a male Sardinian population, and mandate further investigation of its involvement in hypertension in the general population." (PMID 25615575, 2015). "DNA-sequencing detected a 12-nucleotide long thymidine (12T) insertion(ins)/deletion(del) polymorphism within a poly-T sequence (38T vs 26T) in the ATP1A1 5’-regulatory region associated with hypertension in a male Sardinian population." (PMID 25615575, 2015). "Concordantly, lower ATP1A1 expression is expected to lower Na-reabsorption in the kidney thereby decreasing sodium-associated risk for hypertension and sodium-induced endothelial stiffness and dysfunction." (PMID 25615575, 2015). "The 12T-ins (minor) allele is protective for hypertension susceptibility in our Sardinian cohort and exhibits sex-specificity with significantly increased frequencies of ATP1A1 12T-ins alleles only in males (P = 0.035, OR = 0.50)." (PMID 25615575, 2015). "Subsequent studies detected an association of ATP1A1 and DEspR with essential hypertension in humans and revealed a functionally significant DEspRT/CATAAAA-box promoter variant associated with 7.7 mmHg in increased systolic BP in a male Sardinian population." (PMID 24147025, 2013). "In humans, ATP1A1 single-point and haplotype association analyses of a Sardinian hypertensive/normotensive > 60 yrs cohort demonstrated gender-specific association of the ATP1A1 locus with hypertension in males." (PMID 25615575, 2015). "Additionally, the sex-specific effects of the ATP1A1 promoter variants on hypertension susceptibility are also consistent with our studies in the Dahl rat model of salt-sensitive hypertension showing stronger linkage of the ATP1A1 locus with salt-sensitive hypertension in the F2 male population." (PMID 25615575, 2015). "Importantly, these findings are concordant with cumulative evidence obtained in animal models of polygenic hypertension linking ATP1A1 to salt-sensitive hypertension albeit with different molecular basis, and human studies showing association of the ATP1A1 locus with hypertension." (PMID 25615575, 2015). "ATP1A1 interacts with other proteins and modulates hypertension and feed intake." (PMID 34438824, 2021). "The coupling of ATP1A1 mutations to hypertension does not immediately make as much sense as for the potassium channel and calcium regulators." (PMID 28634454, 2017).
glioblastoma (4 papers, 2017 to 2024). The most malignant astrocytic tumor (WHO grade IV). "Promoted proteasome activation and ATP1A1 protein degradation and thereby inhibited ATP1A1 expression in glioblastoma, inhibiting tumor growth and proliferation." (PMID 35011278, 2021). "It has been attempted to combat glioblastoma cells by targeting the ATP1A1 in an orthotopic human glioblastoma xenograft model." (PMID 28484360, 2017). "BF could promote proteasome activation and ATP1A1 protein degradation to inhibit ATP1A1 expression and significantly inhibit tumor growth in glioblastoma." (PMID 35011278, 2021).
kidney cancer (4 papers, 2020 to 2023). Primary or metastatic malignant neoplasm involving the kidney. "Finally, such studies would further elucidate the role of ATP1A1, the expression of which is reduced in prostate, breast, and kidney cancer and associated with poorer survival of kidney cancer patients." (PMID 35150740, 2022). "Kidney cancer patient with SUCLG1, GLDC, SLC12A1, PCK2, ATP1A1 and PDHA1 alteration showed highest mortality." (PMID 32699530, 2020).
prostate carcinoma (4 papers, 2017 to 2021). A carcinoma that arises from epithelial cells of the prostate gland. "For instance, the expression of ATP1A1 is significantly lower in prostate carcinoma than in normal and prostatic hyperplasia glands, and its down-regulation of ATP1A1 leads to a decrease of the Na+, K+-ATPase activity in carcinoma." (PMID 28484360, 2017). "Further, the results demonstrated that Tmprss2 was significantly involved in the “prostate cancer” KEGG pathway, as well as in the “import into cell” term with Per2, Atp1a1, and Arrb1 (GO:0098657, FDR = 3.39 × 10−5)." (PMID 34834564, 2021).